RNU6-706P (RNA, U6 small nuclear 706, pseudogene)
Gene: Small nuclear RNA gene on chromosome 18 (39,034,007 to 39,034,110, forward strand). Ensembl gene ENSG00000253038.
Homologues: Orthologues: chimpanzee U6 (99% identical), macaque U6 (92% identical), mouse Gm55060 (67% identical). Paralogues in human: RNU6-97P (86% identical), RNU6-140P (85% identical), RNU6-1038P (84% identical), RNU6-1122P (84% identical), RNU6-230P (84% identical), RNU6-43P (84% identical), RNU6-529P (84% identical), RNU6-946P (84% identical), RNU6-1011P (83% identical), RNU6-1029P (83% identical), RNU6-1035P (83% identical), RNU6-144P (83% identical), and 1287 more.